ALDH1A1 (aldehyde dehydrogenase 1 family member A1)
Diseases named in the same sentence as ALDH1A1 in open-access papers (continued):
Sharing a sentence is not in itself a finding about the gene and the disease.
breast carcinoma (continued). "In our study, we found that both ALDH1A1 and SFRP1, two commonly important genes for EMT and CSCs, are capable of predicting the overall survival rates for breast cancer." (PMID 33092068, 2020). "Using fluorescent CSC models driven by the expression of ALDH1A 1(aldehyde dehydrogenase 1A1), we confirmed this dynamic phenotypic change in MDA-MB-231 breast cancer cells and to identify Serine/Threonine Kinase 2 (AKT2) as an important player in the process." (PMID 31357505, 2019). "Since ALDH1A1 is expressed in CSC, this approach enables the identification and isolation of CSC, and has proved successful for the MCF7 breast cancer cell line and HCT116 colon cancer cell line." (PMID 31357505, 2019). "We found that ALDH1A1 and HTRA2 regulates CCR2-mediated breast cancer cell growth and cellular invasion in a CCL2/CCR2 context-dependent manner." (PMID 31208996, 2019). "Aldehyde dehydrogenase 1A1 (ALDH1A1), a member of aldehyde dehydrogenase family, is a marker of stemness in breast cancer." (PMID 30541574, 2018). "Assessment of the expression of other BCSC markers -ALDH1A1, EpCAM, CXCR4, and CD133 in stable NRF1 overexpressing CD44+CD24− and CD44+CD24+ subpopulations showed as many as 10 different downstream breast cancer progenitor cell subpopulations." (PMID 30486409, 2018). "Two well-known breast-cancer stem-cell markers, CD44 and ALDH1 family member A1 (ALDH1A1), were examined." (PMID 30513573, 2018). "CSCs in breast cancer are generally characterized with a CD44+/CD24− and/or ALDH1+ (ALDH1A1+) population." (PMID 30558195, 2018). "Of ALDH1 isozymes (ALDH1A1, ALDH1A2 and ALDH1A3), expression of ALDH1A1 is prominent in cancer stem cell, for instance, in human breast cancer cell lines." (PMID 29552329, 2018). "Overexpression of ALDH1A1 and ALDH3A1 isoforms have been shown to result in greater inactivation of cyclophosphamide in breast cancer." (PMID 29902974, 2018). "We next assessed the influence of ALDH1A1 and ALDH1A3 knockdown on breast cancer cell adhesion and migration in vitro." (PMID 28937653, 2017). "Another stem cell marker, aldehyde dehydrogenase family 1 member A1 (ALDH1A1), is correlated with poor prognosis and chemotherapy-resistant breast cancer." (PMID 28851411, 2017). "A number of candidate effectors of SOX11 signalling in DCIS were identified, including ALDH1A1 and HORMAD1, which have established links to breast cancer." (PMID 28707729, 2017). "Expression of ALDH1A1 or ALDH1A3 was knocked down in MDA-MB-468 and SUM159 human breast cancer cells using siRNA." (PMID 28937653, 2017). "High expression of c-Met (MET+) correlated with expression of CSC markers, ALDH1A1 (p < 0.001), ALDH1A3 (p < 0.001), and CD133 (p < 0.001) in breast cancers." (PMID 28966724, 2017). "siRNA was used to knockdown expression of two ALDH1 isozymes (ALDH1A1 and ALDH1A3) in MDA-MB-468 and SUM159 breast cancer cells and generate the following cell populations: 468CON, 468ALDH1A1low, 468ALDH1A3low, 159CON, 159ALDH1A1low, and 159ALDH1A3low." (PMID 28937653, 2017). "A recent study also showed that over-expression of CT45A1, CT antigen in breast cancer cells selectively enhanced the expression of pro-EMT gene, including TWIST1, ALDH1A1." (PMID 27658496, 2016). "For example, ALDH1A1 and ALDH1A3 have been shown to play functional roles in lung and breast cancer cell migration and invasion, although the mechanisms underlying this behavior have not been established." (PMID 26445849, 2016). "It has also been demonstrated that CSC targeting with ALDH1A1-specific CD8+ T cells is followed by decreased spontaneous metastatic burden of HNSCC, pancreatic, and breast cancer cells in vivo." (PMID 26445849, 2016). "For example, the expression of ALDH1A1 or ALDH3A1 is correlated with the resistance of chemotherapeutics in hematopoietic stem cells, breast cancer patient samples, or colorectal cancer xenograft tumors." (PMID 24676703, 2014).
breast carcinoma (continued). "Although ALDH1A1 has been reported to induce radiation resistance in solid tumors, including breast cancer, the exact mechanism is not clear." (PMID 40076923, 2025). "Moreover, knocking down these two isoenzymes, ALDH1A1 and ALDH1A3, resulted in decreased ALDH activity, leading to decreased therapy resistance and metastatic behavior in breast cancer cells." (PMID 39796106, 2024). "Quantification of presence of ALDH1A1 marker suggested that both oral and breast cancer cell lines Unstained cells were considered as negative control and were used to establish the sorting gates." (PMID 39513121, 2024). "Moreover, TNBCs are also enriched in the expression of transcriptional programs coupled to breast cancer stem cells (e.g., CD44, ITGA6/α6 Integrin, ALDH1A1, and CD133/PROM1) and epithelial–mesenchymal transition (EMT) programs." (PMID 39335212, 2024). "A subpopulation of breast cancer CSCs showed both EMT and CSC markers CD44, ABCG2, and ALDH1A1/3, which might serve as identification markers for metastasis‐initiating cells." (PMID 36226253, 2022). "Single-cell RNA-Seq analysis conducted with breast cancer CSCs showed a population with hybrid EMT and CSC markers CD44, ABCG2, and ALDH1A1/3, which might mark the MICs." (PMID 34150761, 2021). "In basal-like breast cancers, ALDH1A3 expression predominates, and expression of ALDH1A3, but not ALDH1A1, correlates significantly with cancer type, tumor grade and metastasis in breast cancer." (PMID 32658903, 2020). "ALDH1A1 is a metabolic enzyme that functions as a pro-invasive factor and stem cell marker, and positively corresponded to CCR2 expression in breast carcinomas." (PMID 31208996, 2019). "In summary, these data indicate that ALDH1A1 is important for CCL2/CCR2-mediated breast cancer cell growth, but not invasion." (PMID 31208996, 2019). "In summary, it is possible that ALDH1A1 expression and activity in DCIS.com and SUM225 CCR2-overexpressing breast cancer cells may facilitate cell growth through metabolites that activate oncogenic pathways." (PMID 31208996, 2019). "Altering ALDH1A1 expression in CCR2-H SUM225, CCR2-KO and parental DCIS.com cells led to changes in spheroid size and PCNA expression, indicating that an important role for ALDH1A1 in breast cancer cell growth regardless of cell line or CCR2 status." (PMID 31208996, 2019). "To test the hypothesis, we first compared the expression of KLF4, ALDH1A1, ALDH1A3, CD44, and CD24 in human breast cancer samples available in TCGA database." (PMID 30038266, 2018). "In human breast cancer cell lines the content of cancer stem cells was correlated with high expression of NF-κB –inducing kinase (NIK) and was also related to elevated expression of ALDH1A1 gene." (PMID 29765532, 2018). "Knockdown of ALDH1A3 but not ALDH1A1 in breast cancer cells decreased ALDH activity, and knockdown of ALDH1A1 reduced breast cancer cell metastatic behavior and therapy resistance relative to control (p < 0.05)." (PMID 28937653, 2017). "Elucidation of the mechanisms by which ALDH1A1, ALDH1A3 and other ALDH isozymes contribute to disease progression could have potentially important implications for the management and treatment of breast cancer in the future." (PMID 28937653, 2017). "The combined in vitro and in vivo data presented in this study suggests that ALDH1A1 and ALDH1A3 both contribute functionally to various steps in the breast cancer metastatic cascade; however, they may do so in different ways." (PMID 28937653, 2017). "ALDH1A1-positive CTCs were also identified from the blood of metastatic breast cancer patients (data not shown)." (PMID 27013581, 2016). "Based on various studies, it appears that the ALDH family has 19 isoforms that are expressed to a greater extent in the cancer of specific areas of the body; for example ALDH1A3 isoform in breast cancer, ALDH7A1 isoform in prostate cancer, and ALDH1A1 in pancreatic cancer." (PMID 28008389, 2016).
breast carcinoma (continued). "The data for this analysis indicated that the prognosis of breast cancer patients with ALDH1A1+ was poorer than that of the ALDH1A1- patients regardless of the indicators used (OS/SS/RS or DFS/MFS/RFS)." (PMID 24938375, 2014). "Although initially surprising, our findings are coherent with a recent analysis in tumor samples from breast cancer patients showing that ALDH1A1 expression is not the primary determinant of ALDH activity as initially believed." (PMID 24498388, 2014). "Consistent with breast cancer stem-cell data, Western blot analysis revealed an inverse relationship between ALDH1A1 and BRCA1 expression in A2780/CP70 cells, suggesting ALDH1A1 expressing ovarian cancer stem-like cells more likely to lose or express low levels of BRCA1." (PMID 25216266, 2014). "The number of integrin β4+ CTCs expressing CD133 and ALDH1A1 stem markers but not CD44+CD24- was increased in metastatic breast cancer as well as in molecular subtypes of breast cancer with poor prognosis (luminal (HER2+) and TNBC) compared with luminal A/B (HER2−) subtype." (PMID 38250718, 2024). "Cultured breast cancer cells MDA-2J2 that are resistant to paclitaxel, doxorubicin, staurosporine, and multikinase inhibitor sorafenib, could be sensitized by ALDH1A1 gene silencing, demonstrating the capacity of ALDH1A1 to mediate resistance to a variety of antineoplastic pharmaceutical agents." (PMID 37298333, 2023). "Although all over-expressed antigens might not be strong immunotherapeutic targets, certain other types of overexpressed antigens have been studied, such as ALDH1A1 and hTERT in CD44+ breast cancer CSCs, HER2 proto-oncogene in glioma CSCs, and CEP55 and COA-1 in colon CSCs." (PMID 36627890, 2022). "Our results support previous studies, which have shown that ALDH1A3 is highly expressed in ALDHbr cells and that ALDH1A1 expression may not be directly related to proliferation and metastasis in breast cancer." (PMID 32423137, 2020). "Overall, our results show that ALDH1A1 expression is not consistent across breast cancer subtypes, and the presence of ALDHbr cells may not be a marker of strong pluripotency or metastatic behavior." (PMID 32423137, 2020). "For instances, a large part of breast cancer cells shows higher level of ALDH1A3, consistent with a previous report claiming ALDH1A3 to be the main contributor in ALDEFLUOR assay in breast cancer, whereas liver cancer and kidney cancer show high level of ALDH1A1." (PMID 30220009, 2019). "Not surprisingly, several ALDH isoforms other than ALDH1A1 have been proved being associated with certain cancers, e.g., ALDH3A1 in lung cancer and prostate cancer and ALDH5A1 in breast cancer." (PMID 30220009, 2019). "However, the contributions of ALDH1A1 and HTRA2 to breast cancer cell growth and invasion may depend on a complex set of factors involving differences in CCL2/CCR2 signaling among breast cancer cell lines." (PMID 31208996, 2019). "Comparing the expression between ALDH1A1 and ALDH2, stronger ALDH2 expression can be found in the tumor stem-like cells of atypical teratoid/rhabdoid tumour (TSC-AT/RT), and in both parental and stem-like tumor cells of breast cancer, prostate cancer, ovarian cancer and glioblastoma (GBM)." (PMID 29552329, 2018). "In breast cancer, mixed results have been reported regarding the specific ALDH1A isoenzyme involved in tumorigenesis and the ALDEFLUORTM assay, with some groups reporting ALDH1A1 as the main enzyme involved and others showing that ALDH1A3 is the accountable isoform." (PMID 26445849, 2016). "We evaluated the association between tumor tissue ALDH1A1/ALDH1A3 mRNA expression and triple-negative breast cancer (TNBC) prognosis in the Shanghai Breast Cancer Survival Study (SBCSS, N=463), Nashville Breast Health Study (NBHS, N=86), and Southern Community Cohort Study (SCCS, N=47)." (PMID 26462023, 2015).
breast carcinoma (continued). "Our findings, coupled with those of other studies, imply that ALDH1A1 alone may not be a robust prognostic factor in breast cancer." (PMID 22112299, 2011). "Notably, inhibition of ALDH1A1 has been shown to sensitize ALDH1A1-enriched pancreatic cancer MIA PaCa-2 cells to gemcitabine; in addition, inhibition of ALDH has been also shown to sensitize ALDH-enriched ovarian and breast cancer cells to chemotherapy and radiotherapy." (PMID 24676703, 2014). "In breast cancer cell lines with high ALDEFLUOR activity, such as MDA-MB-468 cells, ALDH1A3 knockdown significantly decreased the ALDEFLUOR-positive rate, whereas ALDH1A1 knockdown did not have this effect." (PMID 36651035, 2023). "Earlier studies indicate that it is ALDH1A3, not ALDH1A1, that contributes to ALDH activity in basal-like breast cancer cell lines, and ALDH1A3 is reported to positively associate with tumor grade, stage and metastasis." (PMID 32658903, 2020). "ALDH1A1-negative breast cancer tissue displayed strong NOTCH1 staining (1.92 ± 0.37), compared to ALDH1A1-positive breast cancer tissue (0.61 ± 0.11, P = 0.002)." (PMID 23767668, 2013). "In a distinct study, shRNA knock-down data indicated that ALDH1A3, not ALDH1A1, correlated best with ALDH activity in breast cancer stem cells." (PMID 23484127, 2013). "By comparing the CSCs and non-CSCs-like subpopulations separated from a TNBC cell line BT549, and analyzing the correlation between RICH1 and ALDH1A1 in TNBC samples, the negative correlation between RICH1 and CSC properties of breast cancer cells was firstly found in our study." (PMID 35064101, 2022). "At the marker profile, the Quiescent stem-like population expresses the pluripotency markers, while the Progenitor population in breast cancer cells can be marked by CD44 with diminished pluripotency markers and without other CSC markers like ALDH1A1/3 or ABCG2." (PMID 34150761, 2021). "This led us to suspect that ALDH1A1, which is believed to be the key promoter of tumorigenicity in HER2-OE breast cancer, may not play a key role in tumorigenicity." (PMID 32423137, 2020). "Moreover, in breast cancers with high ALDH activity, the expression of the ALDH1 isoform ALDH1A1 did not correlate with high metastasis or poor survival." (PMID 32423137, 2020). "However, the results have shown that cisplatin more specifically targeted progenitor cells, rather than the stem breast cancer cells, with the reduction of the population of CD24−/CD44+ and ALDH1A1 MDA-MB-231 cells being at higher folds in tpMDA, compared to tsMDA." (PMID 33919109, 2021).
ovarian carcinoma (173 papers, 2009 to 2026). A malignant neoplasm originating from the surface ovarian epithelium. "Nevertheless, the association between ALDH1A1 expression and other clinical features of ovarian cancer, including grading, FIGO stage, or residual tumor status, has not been proven in our study." (PMID 36768723, 2023). "The findings in this study demonstrated a new mechanism contributing to the development of PARPi resistance in HR-deficient ovarian cancer and showed the therapeutic potential of combining PARPi and ALDH1A1 inhibition in treating these patients." (PMID 37429899, 2023). "In summary, our study elucidates a new mechanism contributing to PARPi resistance in HR-deficient ovarian cancer and shows the therapeutic potential of combining PARPi and ALDH1A1 inhibition in treating these patients." (PMID 37429899, 2023). "The ALDH1A1 selective inhibitor NCT-501 can synergize with Olaparib to kill epithelial ovarian cancer cells carrying BRCA2 mutations." (PMID 36484016, 2022). "Reduced expression of aldehyde dehydrogenase gene ALDH1A1 is associated with stemness properties as well as platinum resistance of ovarian cancer cells." (PMID 34758842, 2021). "High ALDH1 family member A1 (ALDH1A1) led to nuclear factor-erythroid 2-related factor 2 (Nrf2) activation via p62-associated pathway in ALDH1-high CSC-like ovarian cancer cells." (PMID 34322664, 2021). "The ALDH1A1 subpopulation is associated with an invasive phenotype, clonogenicity, drug resistance, and worse progression-free survival in ovarian cancer patients." (PMID 34064635, 2021). "ALDH1A1 (aldehyde dehydrogenase 1 family member A1) has been used as a cancer stem cell marker and is associated with chemoresistance in ovarian cancer." (PMID 33042843, 2020). "ALDH1A1+ CSCs have been implicated in rendering resistance to the PARPi in BRCA2-mutated epithelial ovarian cancer." (PMID 32776013, 2020). "As clinical evidence, ALDH1A1 expression has been associated with poor clinical outcomes in ovarian cancer patients." (PMID 30166520, 2018). "Overall, our study demonstrated that high ALDH1A1 led to NRF2 activation via p62-associated pathway in ALDH1-high CSC-like ovarian cancer cells." (PMID 30166520, 2018). "The ALDH1A1-positive cell subpopulation has been demonstrated to be associated with chemoresistance in ovarian cancer patients." (PMID 26783961, 2016). "This upregulation occurs in both BRCA1/2-mutated and -WT cells, but only affects PARPi sensitivity in BRCA1/2-mutated cells, further supporting our previous findings that ALDH1A1 inhibitor can only be used to treat HR-deficient ovarian cancer cells in combination with PARPi12." (PMID 37429899, 2023). "However, in preliminary studies, positive association of SALL4 and ALDH1A1 expression proteins were reported separately with advanced FIGO stage in ovarian cancer tissue samples." (PMID 35090523, 2022). "Also, loss of ALDH1A1 triggered DNA damage suggesting that ALDH1A1 plays a genome-protecting role in ovarian cancer stem cells." (PMID 29552329, 2018). "Moreover, ALDH1A1 expression associates with chemoresistance of cultured and xenografted ovarian cancer and pancreatic adenocarcinoma cells." (PMID 25788273, 2015). "Additionally, the ALDH1A1 subpopulation had demonstrated to be associated with chemoresistance in ovarian cancer patients." (PMID 25216266, 2014). "Our previous study has demonstrated that increased expression of aldehyde dehydrogenase 1A1 (ALDH1A1) contributes to PARPi resistance in BRCA2-mutated ovarian cancer cells by enhancing microhomology-mediated end joining (MMEJ) but the mechanism remains unknown." (PMID 37429899, 2023). "ALDH1A1-positive ovarian cancer cells have been shown to contribute to resistance to paclitaxel and topotecan." (PMID 40868269, 2025). "In ovarian cancer, resistant subpopulations exhibiting high ALDH1A1 and S100A4 expression were found to co-localize with lactylation signals, linking metabolic reprogramming directly to spatial stemness niches." (PMID 41583433, 2025).